TEX44 (testis expressed 44)
Synonyms: C2orf57; MGC35154
Tractability: No criterion of Open Targets' tractability assessment is met for any kind of drug.
Gene: Protein-coding gene on chromosome 2 (231,592,864 to 231,594,276, forward strand). Ensembl gene ENSG00000177673.
Subcellular location: Cytoplasm
Gene Ontology:
Molecular function: protein binding
Cellular component: cytoplasm
Genetic constraint (gnomAD): Loss-of-function variants: 0 observed, 0.27 expected, observed/expected ratio (o/e) 0, 90% interval 0 to 1.87. That is too few expected variants to judge how well the gene tolerates losing a copy. Missense variants: 487 observed, 527.71 expected, observed/expected ratio (o/e) 0.92, 90% interval 0.86 to 1. Synonymous variants: 196 observed, 207.91 expected, observed/expected ratio (o/e) 0.94, 90% interval 0.84 to 1.06.
Homologues: Orthologues: chimpanzee TEX44 (97% identical), macaque TEX44 (85% identical), dog TEX44 (49% identical), mouse Tex44 (42% identical), rat Tex44 (42% identical).